SNHG3 (small nucleolar RNA host gene 3)
Diseases named in the same sentence as SNHG3 in open-access papers (continued):
Sharing a sentence is not in itself a finding about the gene and the disease.
cancer (continued). "Small nucleolar RNA host gene 3 (SNHG3) is a newly identified lncRNA with abnormal expression in various cancers." (PMID 32802874, 2020). "We first observed significant overexpression of SNHG3 in cancer cell lines were observed in our cell panel including MGC-803, AGS, BGC-823, SGC-7901, MKN-45, N87 and HGC-27." (PMID 31534128, 2019). "Despite of the well-recognized oncogene roles of SNHG3 in array of human cancers, the mechanistic involvement of SNHG3 in GC is still elusive." (PMID 31534128, 2019). "Small nucleolar RNA host gene 3 (Snhg3) is a long non-coding RNA (lncRNA) that was shown to participate in the tumorigenesis of certain cancers." (PMID 31151411, 2019). "Studies show that SNHG3 regulates migration and invasion pathways in cancer cells." (PMID 41042421, 2025). "The corresponding cancer cells also tend to show increased SNHG3 amounts compared to normal cells." (PMID 41042421, 2025). "High SNHG3 expression level has been associated with advanced cancer stages and patient outcomes in various tumors, suggesting that SNHG3 levels could serve as a potential indicator for diagnosis or prognosis of different cancers." (PMID 41042421, 2025). "Notably, recent years have witnessed a surge in SNHG3 research, particularly focusing on its ceRNA interactions with microRNAs, highlighting its pivotal role in cancer biology and suggesting novel avenues for therapeutic intervention." (PMID 39349640, 2024). "This multifaceted role positions SNHG3 as a central player in cancer progression." (PMID 39349640, 2024). "Our analysis highlights SNHG3's mechanism of action, whereby it competitively binds to microRNAs to modulate the expression of target genes involved in critical cancer-related processes such as proliferation, apoptosis, migration, invasion, and cell-cycle regulation." (PMID 39349640, 2024). "Moreover, integrating emerging technologies such as single-cell sequencing and CRISPR-based functional screens promises to deepen our understanding of SNHG3's precise role in cancer pathogenesis." (PMID 39349640, 2024). "Recent studies elucidated the multifaceted roles of SNHG3 and miR-384 in various cancers." (PMID 39349640, 2024). "SNHG3 expression was significantly upregulated in 16 (out of 33) cancers compared with normal tissues.72% sensitivity, 87% specificity, and an AUC of 0.89 was observed for cancer detection." (PMID 36980276, 2023). "Third, in vitro functional assays demonstrated that knockdown of BMI1 could significantly attenuate the cancer‐promoting effect of SNHG3 overexpression, suggesting that the SNHG3/c‐MYC/BMI1 axis may play an important regulatory role in BLCa." (PMID 36208024, 2023). "Patients with high RCC1/SNHG3/SNHG12 expression in pan-cancer have poor early OS." (PMID 36148010, 2022). "In breast cancer, SNHG3 functions as a miRNA sponge to promote cancer cell growth and migration." (PMID 36148010, 2022). "The pan-cancer correlations between RCC1/SNHG3/SNHG12 and immune checkpoints were displayed." (PMID 36148010, 2022). "Previous studies have indicated that SNHG3 could acted as ceRNA to regulate cancer biological process through binding microRNA." (PMID 33596916, 2021). "A growing number of studies have shown that SNHG3 plays a crucial role in the development and prognosis of a variety of malignancies.SNHG3 may represent a valuable prognostic biomarker and therapeutic target in various cancers." (PMID 33292213, 2020). "Previous studies have demonstrated the role of lncRNA SNHG3 in cancers." (PMID 32248648, 2020). "Collectively, SNHG3 may be a promising biomarker for diagnosis and target for therapy in various cancers." (PMID 32802874, 2020). "Thus, we preformed this meta-analysis and review, for the first time, to identify the clinical role of SNHG3 in human cancers and explore its functions." (PMID 32802874, 2020). "This suggests that SNHG3 may be critical in regulating angiogenesis in cancer." (PMID 41042421, 2025).
cancer (continued). "Additionally, the functions of SNHG3 in cancer have been steadily revealed." (PMID 34970559, 2021). "All results above demonstrated that SNHG3 could be a prognostic factor for cancer patients' OS." (PMID 32802874, 2020). "However, most researches identified SNHG3 as an oncogene in various cancers." (PMID 32284745, 2020). "Small Nucleolar RNA Host Gene 3 (SNHG3) is a lncRNA and frequently dysregulated in various human cancers." (PMID 39349640, 2024). "Small nucleolar RNA host gene 3 (SNHG3), located at 1p35.3 and predominantly found in the nucleus and mitochondria, emerges as a key player in cancer development, evidenced by its upregulated expression in tumors compared to normal tissues." (PMID 39349640, 2024). "CASC9, POU3F3, SNHG3, CDKN2B-AS1, and ZEB2-AS1 are predicted to sponge several miRNAs (in cancer cells) to promote cancer proliferation." (PMID 37190145, 2023). "However, in BLCa, SNHG3 may regulate cancer progression through different pathways." (PMID 36208024, 2023). "The expression of SNHG3 and SNHG12 in pan-cancer showed high similarity with the expression of RCC1." (PMID 36148010, 2022). "Consistent with our results, SNHG3 and SNHG15 have been reported to be significantly upregulated in several types of cancer." (PMID 32126023, 2020). "Therefore, we proposed whether CAF-secreted exosomal SNHG3 could regulate miRNA in cancer cells." (PMID 31956955, 2020). "Additionally, the Western blot analysis revealed that the knockdown of SNHG3 significantly reduced the protein levels of proteins involved in the cell cycle (CDK6, CDK4, and Cyclin D1) as well as cancer metastasis (N-Cadherin, Vimentin, and MMP9)." (PMID 37348024, 2023). "Nonetheless, previous studies have not dealt with the regulatory effect of SNHG3 on miR-152-3p to influence onset and progression of cancer, and relative studies on downstream targets and the modulatory mechanism of miR‐152‐3p in PCa are warranted." (PMID 35123415, 2022). "Recent studies have shown that SNHG3 and SNHG12 are dysregulated in a variety of cancers." (PMID 36148010, 2022). "SNHG3 was previously found to exert oncogenic roles in a plethora of cancers: Based on current studies, SNHG3 was involved in TGF-β, NOTCH, JAK2/STAT3 and HGF pathway to promote cancer cell proliferation, invasion and inhibit apoptosis rate." (PMID 33596916, 2021). "Recent findings showed lncRNA small nucleolar RNA host gene 3 (SNHG3) functioned as an endogenous sponge for miR-330, thereby modulating the expression of pyruvate kinase M1/2 (PKM), which led to a down-regulation in cancer cell mitochondrial activity and promoted cancer growth and glycolysis." (PMID 32957712, 2020).
infection (1 paper, 2022). The state of being infected such as from the introduction of a foreign agent such as serum, vaccine, antigenic substance or organism. "The silencing of SNORA/Ds encoded within RPS11 (SNORD35B), SNHG3 (SNORA73A, SNORA73B), and SNHG1 (SNORD22, SNORD25, SNORD26, SNORD27, SNORD28, SNORD29, SNORD30, SNORD31) inhibited infection with influenza A virus." (PMID 36430145, 2022).
neurological disorders (1 paper, 2026). "Recent studies have further uncovered the essential role of SNHG3 in neurological disorders, such as brain injury, spinal cord injury, and drug-induced nerve injury." (PMID 41675449, 2026).
SNHG3 also shares sentences with these, for which no sentence is quoted: laryngeal squamous cell carcinoma (5 papers); neuroblastoma (3); endometrial carcinoma (2); leukemia (2); pancreatic cancer (2); autoimmune disorders (1); bladder urothelial carcinoma (1); cardiovascular diseases (1); colon adenocarcinoma (1); Hypoglycemia (1); Insulin resistance (1); ischaemia (1); lung squamous cell carcinoma (1); metastasis (1); neutropenia (1); oral cancer (1); rectum adenocarcinoma (1); renal cell carcinoma (1); steatosis (1); stomach adenocarcinoma (1).